TDRD6 (tudor domain containing 6)
Description:
Tudor domain-containing protein involved in germ cell development, more specifically the formation of chromatoid body (during spermiogenesis), Balbiani body (during oogenesis), germ plasm (upon fertilization), and for proper miRNA expression and spliceosome maturation (By similarity). Essential for RNA-dependent helicase UPF1 localization to chromatoid body, for UPF1-UPF2 and UPF1-DDX4 interactions which are required for mRNA degradation, using the extended 3' UTR-triggered nonsense-mediated mRNA decay (NMD) pathway. Involved in spliceosome maturation and mRNA splicing in prophase I spermatocytes through interaction with arginine N-methyltransferase PRMT5 and symmetrically arginine dimethylated SNRPB (small nuclear ribonucleoprotein-associated protein) (By similarity).
Synonyms: CT41.2; NY-CO-45; bA446F17.4; SPATA36; TDR2
Tractability: No criterion of Open Targets' tractability assessment is met for any kind of drug.
Gene: Protein-coding gene on chromosome 6 (46,687,875 to 46,704,319, forward strand). Ensembl gene ENSG00000180113.
Subcellular location: Cytoplasm
Subcellular location (Human Protein Atlas): Cytosol; Endoplasmic reticulum; Vesicles
Pathways (Reactome):
Gene expression (Transcription): PIWI-interacting RNA (piRNA) biogenesis
Gene Ontology:
Biological process: P granule organization; piRNA processing; spermatogenesis
Cellular component: chromatoid body; cytoplasm; P granule
Genetic constraint (gnomAD): Loss-of-function variants: 169 observed, 151.5 expected, observed/expected ratio (o/e) 1.12, 90% interval 0.98 to 1.27. The upper end of that interval is the gene's LOEUF score, 1.27, which puts it in group 5 of 6, group 1 being the genes least tolerant of losing a copy. Missense variants: 2,817 observed, 2,414.5 expected, observed/expected ratio (o/e) 1.17, 90% interval 1.13 to 1.2. Synonymous variants: 962 observed, 888.3 expected, observed/expected ratio (o/e) 1.08, 90% interval 1.03 to 1.14.
Homologues: Orthologues: chimpanzee TDRD6 (99% identical), macaque TDRD6 (95% identical), pig TDRD6 (78% identical), rabbit TDRD6 (77% identical), dog TDRD6 (77% identical), rat Tdrd6 (74% identical), mouse Tdrd6 (72% identical), guinea pig TDRD6 (56% identical), tropical clawed frog tdrd6 (33% identical), zebrafish tdrd6a (28% identical), zebrafish tdrd6b (21% identical), Drosophila melanogaster tud (15% identical). Paralogues in human: TDRD15 (22% identical), TDRD1 (11% identical), TDRD7 (8% identical), TDRD5 (7% identical), TDRKH (5% identical), TDRD10 (3% identical).
Diseases named in the same sentence as TDRD6 in open-access papers:
TDRD6 is named in the same sentence as 17 diseases in open-access papers, as found by Europe PMC text mining. Sharing a sentence is not in itself a finding about the gene and the disease. The quoted sentences say what the papers report.
male infertility (5 papers, 2012 to 2025). The inability of the male to effect fertilization of an ovum after a specified period of unprotected intercourse. "Biallelic TDRD6 variants have been previously reported in male infertility patients with severe OAT and sperm‐derived embryonic arrest." (PMID 39764564, 2025). "Here, we present two cases of male infertility linked to novel TDRD6 variants, associated with oligoasthenoteratozoospermia (OAT) and early embryonic arrest." (PMID 39764564, 2025). "Here, we demonstrated that proper AOA is an effective therapeutic treatment for male infertility caused by TDRD6 variants in humans and can enhance oocyte activation ability, improve embryo quality, and lead to the conception of a healthy baby." (PMID 39764564, 2025). "The loss of TDRD6 results in male infertility and disruption of CB architecture of which a remnant “ghost body” is left." (PMID 27149095, 2016). "Altogether, our findings provide necessary evidences to support the idea that the homozygous LOF variant in TDRD6 induces male infertility with severe OAT, suggesting that TDRD6 could be a useful genetic diagnostic target for male infertility." (PMID 39331689, 2024). "Based on a comprehensive literature review of human disease symptoms and gene‐edited mouse phenotypes, we found that the testis‐specific gene TDRD6 was the gene that was most significantly associated with male infertility, especially OAT, among all the screened genes." (PMID 39331689, 2024). "Taken together, these results indicate that Tdrd6 defects lead to decreased Mos expression in PN4 zygotes, ultimately resulting in early embryonic arrest and male infertility in Tdrd6−/− mice." (PMID 39764564, 2025). "A similar fragmentation of chromatoid bodies has been observed in other mouse mutants of RNA processing pathway proteins with male infertility phenotype, implying importance of their structural integrity (Miwi, Tdrd5, and Tdrd6)." (PMID 23166510, 2012). "Utilizing Tdrd6 knockout mice that we generated via CRISPR-Cas9 genome editing (referred to as Tdrd6−/−), we discovered that Tdrd6 depletion resulted in male infertility but had a negligible impact on piRNA biogenesis in mouse testes, consistent with previous findings." (PMID 38491008, 2024).
Infertility (3 papers, 2022 to 2025). "According to whole exome sequencing (WES) analysis, we detected novel TDRD6 variants in two infertile male individuals from two independent Chinese families with OAT and early embryonic arrest during ICSI treatment." (PMID 39764564, 2025). "In summary, we identified a novel homozygous LOF variant c.G1825T/p.Gly609X in TDRD6 in an infertile man with severe OAT." (PMID 39331689, 2024). "In this study, we identified one homozygous LOF variant (c.G1825T/p.Gly609X) in TDRD6 in one infertile patient with severe OAT by WES." (PMID 39331689, 2024). "Here, one homozygous loss‐of‐function (LOF) variant in TDRD6, c.G1825T/p.Gly609X, was identified in an infertile patient with severe OAT by whole‐exome sequencing (WES) and Sanger confirmation." (PMID 39331689, 2024). "STRING and Cytoscape analyses presented seven genes, i.e., DDX5, TNP2, DDX3Y, TDRD6, SOHL2, DDX31, and SYCP3, as the hub genes involved in infertility with VASA co-function and protein–protein interaction." (PMID 36241908, 2022). "The ratio of infertility genes expression: DDX5, TNP2, DDX3Y, TDRD6, SOHL2, DDX31, and SYCP3 in infertility cell (azoospermia) in comparison to a normal cell." (PMID 36241908, 2022).
oligoasthenoteratozoospermia (2 papers, 2024 to 2025). A form of male infertility that is characterized by a combination of low number or oligozoospermia, poor motility or asthenozoospermia, and abnormal shape or teratozoospermia of sperms. "In 2018, a homozygous missense variant of the TDRD6 gene was considered the cause of oligoasthenoteratozoospermia (OAT), indicating that TDRD6 may be a new gene associated with OAT." (PMID 39174853, 2024).
colon cancer (1 paper, 2020). "In our study, it was found that TDRD5, TDRD6 and TDRD7 are differentially expressed in CRC, and further studies on the role of these three genes in colon cancer are needed." (PMID 32828126, 2020).
osteosarcoma (1 paper, 2021). A usually aggressive malignant bone-forming mesenchymal neoplasm, predominantly affecting adolescents and young adults. "Our results showed that compared with osteoblasts, CPEB3, EIF4E3, RBM34, RPS27L, RPS29 and TDRD6 were down-regulated in U2OS and 143B, while NXT2, TERT, TLR8 and ZC3HAV1 were up-regulated in osteosarcoma cells." (PMID 34926575, 2021).
cancer (4 papers, 2020 to 2021). A tumor composed of atypical neoplastic, often pleomorphic cells that invade other tissues. "Some identified prognostic DE RBPs have not been associated with cancers, such as CELF4, POP1, TDRD6, TDRD7, LRRFIP2, and ZC3H12C." (PMID 33224957, 2020). "TDRD6 and TTK are promising targets for cancer vaccines that could activate a number of immune cells, especially T cells and B cells." (PMID 32728493, 2020). "Moreover, two CT genes, TDRD6 and TTK, were positively correlated with a number of immune cells, especially the CD4+/CD8+ T cells, implying strong host immune reactions to these two cancer antigens." (PMID 32728493, 2020). "But so far, TDRD6, NXT2, RBM34 have not been described in cancer." (PMID 34926575, 2021).
tumor (3 papers, 2020 to 2022). "TDRD6 and TTK are promising T cell and B cell targets for tumor vaccines." (PMID 32728493, 2020).
TDRD6 also shares sentences with these, for which no sentence is quoted: breast carcinoma (2 papers); autoimmune disease (1); Azoospermia (1); hypopituitarism (1); liver cancer (1); lymphocytic hypophysitis (1); neurodegenerative disease (1); prostate carcinoma (1); teratozoospermia (1); thyroid cancer (1).